MAGEA4 (MAGE family member A4)
Diseases named in the same sentence as MAGEA4 in open-access papers (continued):
Sharing a sentence is not in itself a finding about the gene and the disease.
MAGEA4 also shares sentences with these, for which no sentence is quoted: esophageal squamous cell carcinoma (8 papers); myxoid/round cell liposarcoma (8); soft tissue sarcoma (8); hepatocellular carcinoma (6); head and neck squamous cell carcinoma (5); colorectal cancer (4); oral squamous cell carcinoma (4); Hodgkins lymphoma (3); pancreatic cancer (3); prostate carcinoma (3); triple-negative breast carcinoma (3); desmoid tumor (2); embryonal carcinoma (2); endometrial cancer (2); esophageal tumor (2); hematological malignancies (2); leiomyosarcoma (2); liposarcoma (2); lymphoma (2); metastatic tumors (2); myxoid liposarcoma (2); round cell liposarcoma (2); serous carcinomas (2); squamous cell carcinoma (2); undifferentiated pleomorphic sarcoma (2); acute myeloid leukemia (1); adenoid cystic carcinoma (1); angiosarcoma (1); Arthritis (1); bladder tumors (1).
A further 41 diseases each share a sentence with MAGEA4 in 1 paper.